PNPLA3 (patatin like domain 3, 1-acylglycerol-3-phosphate O-acyltransferase )
Diseases named in the same sentence as PNPLA3 in open-access papers (continued):
Sharing a sentence is not in itself a finding about the gene and the disease.
chronic kidney disease (8 papers, 2015 to 2025). Impairment of the renal function secondary to chronic kidney damage persisting for three or more months. "In addition to its association with MASLD, some prospective studies have also suggested that PNPLA3 variants are associated with chronic kidney disease, and patients carrying PNPLA3 variants have a higher risk of early glomerular and tubular damage." (PMID 40881642, 2025). "An interesting study in which 157 Caucasian patients were enrolled with type 2 diabetes evidenced the role of the PNPLA3 M variant in increasing the risk of chronic kidney disease (CKD)." (PMID 34198853, 2021). "In addition, the PNPLA3 genotype has been elucidated as a modifier of NAFLD-associated metabolic systemic diseases such as carotid atherosclerosis and chronic kidney disease." (PMID 33059586, 2020). "Beyond PNPLA3, several genetic variants have been implicated in the shared pathophysiology of metabolic dysfunction-associated steatotic liver disease (MASLD) and chronic kidney disease (CKD)." (PMID 41007724, 2025).
carotid atherosclerosis (6 papers, 2013 to 2025). A thickening and loss of elasticity of the walls of carotid arteries that occur with formation of atherosclerotic plaques. "PNPLA3 GG genotype is associated with higher severity of carotid atherosclerosis in younger patients with NAFLD." (PMID 24069270, 2013). "The main limitation of this study lies in its cross-sectional nature, unable to identify pathogenic mechanisms(s) linking PNPLA3 genotype and carotid atherosclerosis, and in the relative low number of patients younger 50 years." (PMID 24069270, 2013). "From a clinical point of view, our data confirm that NAFLD patients are at high risk of carotid atherosclerosis, especially in the presence of classical risk factors, in younger patients with PNPLA3 GG genotype, and in patients aged 50 or more." (PMID 24069270, 2013). "The PNPLA3 G/G genotype was associated with not only the risk for NAFLD, but also a higher severity of carotid atherosclerosis in NAFLD patients." (PMID 26200108, 2015).
alcohol abuse (5 papers, 2015 to 2025). The use of alcoholic beverages to excess, either on individual occasions ("binge drinking") or as a regular practice. "One of the primary genetic risk factors for developing liver-related complications of alcohol use disorder is the presence of the G allele in the rs738409 single nucleotide polymorphism (SNP) in the gene encoding patatin-like phospholipase domain-containing protein 3 (PNPLA3)." (PMID 40731922, 2025). "Most importantly, the prevalence of established risk factors for advanced fibrosis or accelerated fibrosis progression (such as prior alcohol abuse, HCV-GT3, low CD4+ nadir, etc.)was comparable between patients with and without PNPLA3 risk alleles." (PMID 26599080, 2015).
hepatitis C (5 papers, 2013 to 2020). "The genetic factors that influence the evolution of hepatitis C are being studied, including the rs738409 polymorphism of the patatin-like phospholipase domain containing 3 (PNPLA3) gene." (PMID 29258449, 2017).
hyperlipidemia (5 papers, 2020 to 2025). "In our study, post-prandial secretion of VLDL, the predominant post-prandial lipoprotein associated with hyperlipidaemia, was lower in participants homozygous for TM6SF2 or PNPLA3, but fasting ApoB levels were normal." (PMID 37484212, 2023).
hypertriglyceridemia (5 papers, 2017 to 2025). A laboratory test result indicating elevated triglyceride concentration in the blood. "In a multivariable analysis, hypertriglyceridemia, BMI, and the PNPLA3 GG genotype were identified as factors associated with MAFLD." (PMID 37632067, 2023). "The protective role of HBV infection in glycolipid metabolism and related diseases, which are characterized by lower prevalence of NAFLD, hypertriglyceridemia, MetS, and IR rate, are likely to counteract the effect of PNPLA3 polymorphism." (PMID 28695131, 2017).
sarcopenia (5 papers, 2021 to 2025). Progressive decline in muscle mass due to aging which results in decreased functional capacity of muscles. "It is characterized by visceral obesity, sarcopenia, and significant genetic determinants (variants of PNPLA3, TM6SF2, and MBOAT7) in normal BMI individuals." (PMID 41189623, 2025). "In multiple logistic regression analysis, relevant risk factors for a higher FAST score were identified as follows: age, ALT, HOMA-IR, sarcopenia, PNPLA3 genotype (dominant model), PC ae C40:6, lysoPC a C18:2, SM C24:0, and tyrosine." (PMID 36984884, 2023). "A model combining clinical (age, sex, ALT, HOMA-IR, and sarcopenia), genomic (PNPLA3 rs738409), and metabolomic (PC ae C40:6, lysoPC a C18:2, SM C24:0, and tyrosine) parameters achieved the highest c-index (0.948) for the prediction of high-risk NASH." (PMID 36984884, 2023). "The present exploratory study demonstrated that the combination of clinical (age, ALT, HOMA-IR, and sarcopenia), metabolomic (sphingolipids, glycerophospholipids, and tyrosine), and genomic (PNPLA3 genotype) biomarkers accurately predicted a higher FAST score (>0.35)." (PMID 36984884, 2023).
alcoholic hepatitis (4 papers, 2019 to 2022). Acute hepatitis resulting from ingestion of alcohol. "In another study, patients who survived the first 90 days after severe alcoholic hepatitis and achieved abstinence had a worse outcome, if they were homozygous for the PNPLA3 rs738409 G-allele." (PMID 33917196, 2021).
Impaired glucose tolerance (4 papers, 2012 to 2023). An abnormal resistance to glucose, i.e., a reduction in the ability to maintain glucose levels in the blood stream within normal limits following oral or intravenous administration of glucose. "Recent studies have identified genetic and clinical risk factors for lean NAFLD including the association of the PNPLA3 rs738409 gene, impaired glucose tolerance, and unfavorable adipokine profiles characterized by low adiponectin concentrations." (PMID 37507409, 2023). "The present study points to an association of the common rs738409 minor G-allele of PNPLA3 with decreased levels of fasting serum TAG and total serum cholesterol in individuals with impaired glucose tolerance." (PMID 22792295, 2012).
primary sclerosing cholangitis (4 papers, 2013 to 2022). "Pnpla3 variant was found to be a risk factor for reduced survival of males with primary sclerosing cholangitis." (PMID 34327512, 2021). "According to our results, genetic testing for the common PNPLA3 variant could improve diagnostic and therapeutic approaches in patients with primary sclerosing cholangitis, particular in the presence of a DS." (PMID 23505555, 2013).
co-infection (3 papers, 2015 to 2017). "In conclusion, our results, in combination with previous evidence, confirm a role of PNPLA3 rs738409 in fibrosis progression in HIV/HCV co-infection." (PMID 27973562, 2016).
gout (3 papers, 2018 to 2025). A condition characterized by painful swelling of the joints, which is caused by deposition of urate crystals. "In conclusion, this study found that PNPLA3 inhibition increased the risk of high uric acid levels and gout." (PMID 40881642, 2025). "In this MR study, genetically predicted PNPLA3 inhibition was associated with an increased risk of elevated urate levels and gout." (PMID 40881642, 2025). "In this study, we proposed a two-sample MR approach to explore the association between PNPLA3 inhibition and gout." (PMID 40881642, 2025). "The objective of this study was to ascertain the impact of PNPLA3 inhibition on the risk of gout through Mendelian randomization." (PMID 40881642, 2025). "The findings indicate that LDL-C and ApoA1 are improbable mediators of the genetically predicted association between PNPLA3 inhibition and gout." (PMID 40881642, 2025). "This PheWAS also indicates an inverse association between the PNPLA3 risk allele and presence of gout." (PMID 31311600, 2019). "Additionally, PNPLA3 inhibition was associated with elevated TG levels, which partially mediated the relationship between PNPLA3 inhibition and an increased risk of gout." (PMID 40881642, 2025). "Furthermore, additional research is needed to determine if the inhibition of PNPLA3 due to prolonged pharmacological use elevates the risk of gout." (PMID 40881642, 2025). "As far as we know, this is the first study on the association between PNPLA3 inhibition and gout." (PMID 40881642, 2025). "Genetically predicted PNPLA3 inhibition resulted in an increased risk of gout (OR: 1.83, 95% CI: 1.49 to 2.26, p=1.44 × 10−8) and idiopathic gout (OR: 2.42, 95% CI: 1.60 to 3.65, p=2.81 × 10−5), but not for gout due to impaired renal function (OR: 1.25, 95% CI: 0.37 to 4.22, p=7.23 × 10−1)." (PMID 40881642, 2025). "Moreover, we discovered that genetically predicted PNPLA3 inhibition could elevate the risk of idiopathic gout, gout, and high urate levels." (PMID 40881642, 2025). "However, blood TG may mediate the genetically predicted association between PNPLA3 inhibition and gout and urate." (PMID 40881642, 2025). "Additionally, these analyses indicated that blood TG levels may act as a mediator in the relationship between PNPLA3 inhibition and the increased risk of gout." (PMID 40881642, 2025). "Further analysis revealed that PNPLA3 inhibition might elevate TG, LDL-C, and ApoA1 levels, and TG may partially mediate the association between PNPLA3 inhibition and gout." (PMID 40881642, 2025). "Nevertheless, ARO-PNPLA3, a prospective therapeutic agent for MASLD, is still unknown for the effect of PNPLA3 inhibition on urate and gout." (PMID 40881642, 2025). "Furthermore, given the strong correlation between lipids and MASLD, we employed a two-step MR to assess the potential role of plasma lipids in the relationship between PNPLA3 and gout." (PMID 40881642, 2025). "In addition, PNPLA3 inhibition also increased triglyceride (TG) levels, which partially mediate the relationship between PNPLA3 inhibition and gout." (PMID 40881642, 2025). "Subsequently, we confirmed whether TG, LDL-C, and ApoA1 played roles in the genetically predicted link between PNPLA3 inhibition and gout." (PMID 40881642, 2025). "Leave-one-out analysis showed that the association between PNPLA3 inhibition and gout and urate was not significantly affected by any single SNP." (PMID 40881642, 2025). "Unexpectedly, we found a negative correlation between PNPLA3 variant rs738409 with gout or gouty arthropathy (p = 1.09 × 10− 4, beta = − 0.12, SE = 0.03)." (PMID 31311600, 2019).
liver inflammation (3 papers, 2014 to 2022). "The Dallas Heart Study identified PNPLA3 (rs738409) as being strongly associated with elevated hepatic TG levels and liver inflammation." (PMID 35251371, 2022). "Mutant PNPLA3 and wild-type NAFLD showed the same levels of adipocyte inflammatory gene expression, while hepatitis-related pathologies were significantly higher in PNPLA3 mutant patients." (PMID 24786095, 2014).
prediabetes (3 papers, 2020 to 2025). "Therefore, a future study should be conducted on patients with BMI greater >30 to further analyze the significance of this interaction between PNPLA3 gene and BMI in the contest of prediabetes and progression of NAFLD to significant fibrosis." (PMID 33520810, 2020). "Change in liver fat between groups were in the same direction as for the primary analysis and statistically significant for individuals with T2D (not for prediabetes), those without NAFLD (not NAFLD) as well as for individuals with the I148M PNPLA3 CC-genotype (not CG/GG)." (PMID 41390743, 2025).
autoimmune hepatitis (2 papers, 2021 to 2022). Hepatitis caused by autoantibodies. "Interestingly, carriage of the PNPLA3-I148M variant confers a poorer prognosis in other liver diseases including alcohol-related liver disease, and autoimmune hepatitis." (PMID 33544287, 2021).
chronic hepatitis B (2 papers, 2014 to 2017). "Except for the results obtained from normal and CHB+HS groups, another noticeable observation of the present study lied in that PNPLA3 rs1010023 did not associate with the levels of TG, insulin, FBG, and HOMA-IR in chronic hepatitis B patients." (PMID 28695131, 2017).
End Stage Liver Disease (2 papers, 2016 to 2025). Final stage of a liver disease when the liver failure is irreversible and LIVER TRANSPLANTATION is needed. "We analyzed the PNPLA3 rs738409 genotypic distribution in 28 HIV/HCV-coinfected individuals who underwent a liver transplant because of end-stage liver disease, as well as, in 19 coinfected and non-cirrhotics controls (study population 2)." (PMID 27973562, 2016).
hyperglycaemia (2 papers, 2012 to 2025). "Future studies should stratify study participants according to glucose-tolerance status (i.e. normoglycaemia and hyperglycaemia) or include information on 2-hour OGTT plasma glucose levels to assess the effect of the PNPLA3 rs738409 G-allele on lipid levels." (PMID 22792295, 2012). "Moreover, as lipogenesis is influenced by availability of glucose and PNPLA3 expression is influenced by glucose-levels we aimed to examine whether the effect of PNPLA3 rs738409 on metabolic traits is influenced by hyperglycaemia." (PMID 22792295, 2012).
Hyperinsulinemia (2 papers, 2012 to 2023). An increased concentration of insulin in the blood. "Furthermore, differences were observed in genes contributing to fatty acid, cholesterol and triglyceride metabolism (FATP2, ELOVL6, PNPLA3, SREBF1) and in genes involved in regulating lipolysis (ANGPTL4) between the insulin-resistant and -sensitive subjects especially during hyperinsulinemia." (PMID 22471940, 2012).
hyperuricemia (2 papers, 2014 to 2022). An abnormally high level of uric acid. "A PNPLA3 SNP (rs738409) is associated with hyperuricemia in a Japanese population." (PMID 35813212, 2022). "Thus, PNPLA3 and IGF1R variants might be linked to hyperuricemia and gout by affecting lipid metabolism and oxidative stress." (PMID 35813212, 2022).
insulin dependent diabetes mellitus (2 papers, 2015 to 2019). "Three SNP-diagnosis pairs passed the PheWAS significance threshold: rs9273349 (HLA-DQB1) and E06 (thyroditis); rs9273349 (HLA-DQB1) and E10 (type-1 diabetes); and rs2281135 (PNPLA3) and K76 (non-alcoholic liver diseases, including NAFLD)." (PMID 30978214, 2019).
myelofibrosis (2 papers, 2020 to 2021). A partial or complete replacement of the bone marrow stroma by fibrous tissue. "By screening a clinical compound library targeting specific signaling pathways active in primary human hepatocytes, we identified momelotinib, a drug evaluated in clinical trials to treat myelofibrosis, as a potent down-regulator of PNPLA3 expression, across all genotypes." (PMID 33036387, 2020).
renal dysfunction (2 papers, 2015 to 2019). "We aimed to clarify the associations of the PNPLA3 polymorphism with the risk of NAFLD and/or renal dysfunction, while also paying careful attention to the weight status of the subjects." (PMID 26200108, 2015). "After adjustment for confounders, NAFLD (OR, 4.7; 95% CI, 1.5–14.8; padj = 0.007), but not the PNPLA3 gene variant, emerged as the main independent predictor of renal dysfunction." (PMID 31505904, 2019). "The patatin-like phospholipase 3 (PNPLA3) polymorphism rs738409 (c.444C>G) is associated with the risk of NAFLD and/or renal dysfunction; however, the influence of the weight status on the associations remains unknown." (PMID 26200108, 2015). "The findings of this study suggest that carriers of the PNPLA3 G/G genotype with a normal weight status should nevertheless be carefully monitored for the presence of NAFLD and/or renal dysfunction." (PMID 26200108, 2015).
acne (1 paper, 2018). An inflammatory process of the sebaceous glands which is characterized by comedones, nodules, papules and/or pustules on the skin. "However, concomitant inverse associations with multiple other endpoints, including acne and high plasma cholesterol levels, indicate potential clinically relevant on-target ADEs that should be considered in decisions to progress PNPLA3 inhibitors toward clinical development." (PMID 30327483, 2018).
arteriolosclerosis (1 paper, 2025). The thickening of the wall of the small arteries and arterioles. "In addition, PNPLA3 polymorphism was negatively correlated with aortic stiffness, which is a marker of arteriolosclerosis and vascular ageing." (PMID 40244110, 2025).
arteriosclerosis (1 paper, 2019). A vascular disorder characterized by thickening and hardening of the walls of the arteries. "This study aimed to clarify the factors related to subclinical arteriosclerosis, including the histopathological severity of the disease and PNPLA3 gene polymorphisms, in NAFLD patients." (PMID 31721770, 2019).
diabetic nephropathy (1 paper, 2020). "Interestingly, the significant association between the PNPLA3 I148M variant and increased risk of kidney dysfunction was independent of established renal risk factors and severity of FLD, suggesting that the PNPLA3 I148M might be directly involved in the pathophysiology of diabetic nephropathy." (PMID 33102799, 2020).
glioblastoma (1 paper, 2025). The most malignant astrocytic tumor (WHO grade IV). "This study identified six PMRGs (SARDH, ACHE, ADSL, PNPLA3, MAPK1 and SREBF2) as potential prognostic biomarkers for glioblastoma." (PMID 40313243, 2025).
Hyperbilirubinemia (1 paper, 2022). An increased amount of bilirubin in the blood. "The findings of this genetic association study suggest that UGT1A1 and PNPLA3 were associated with increased risk of hyperbilirubinemia and elevated ALT and AST levels in independent multinational and ancestrally diverse cohorts treated for ALL." (PMID 36580335, 2022). "In this genetic association study of 3557 children, adolescents, and young adults receiving ALL therapy, variants in UGT1A1 and PNPLA3 were associated with hyperbilirubinemia and elevated alanine aminotransferase and aspartate aminotransferase levels, respectively." (PMID 36580335, 2022). "Patients of African ancestry had a lower incidence of hyperbilirubinemia, even though they had a higher risk allele frequency for UGT1A1rs887829 and a lower frequency of the PNPLA3 risk allele; thus, we were unable to identify a genetic basis for their lower hyperbilirubinemia." (PMID 36580335, 2022).
hypogonadism (1 paper, 2025). A disorder characterized by decreased function of the gonads. "Protein-coding variants in several liver genes, such as PNPLA3, GCKR, SLCO1B1, SERPINA1, HGFAC, and UGT2B15, were significantly associated with total testosterone levels and hypogonadism risk." (PMID 40316537, 2025).
injury (1 paper, 2015). Damage inflicted on the body as the direct or indirect result of an external force, with or without disruption of structural continuity. "PNPLA3 polymorphism rs738409 was recently found to be associated with higher susceptibility to advanced forms of liver injury." (PMID 26389885, 2015).
kidney cancer (1 paper, 2024). Primary or metastatic malignant neoplasm involving the kidney. "Furthermore, recent evidence suggests that the PNPLA3 p.I148M variant may also play a role in the development of liver and kidney cancer." (PMID 39797231, 2024).
lipid metabolism disorders (1 paper, 2025). "This study identifies FADS1, FADS2, GLB1, and PNPLA3 as key genes integrating both lipid metabolism disorders and inflammation in MAFLD, with potential diagnostic implications." (PMID 41007773, 2025).
osteoporosis (1 paper, 2026). A condition of reduced bone mass, with decreased cortical thickness and a decrease in the number and size of the trabeculae of cancellous bone (but normal chemical composition), resulting in increased fracture incidence. "PNPLA3 is a gene related to metabolism, and a previous study reported its association with osteoporosis." (PMID 41515648, 2026).